IFI44 (interferon induced protein 44)
Diseases named in the same sentence as IFI44 in open-access papers (continued):
Sharing a sentence is not in itself a finding about the gene and the disease.
head and neck squamous cell carcinoma (3 papers, 2020 to 2021). A squamous cell carcinoma that arises from any of the following anatomic sites: lip and oral cavity, nasal cavity, paranasal sinuses, pharynx, larynx, and salivary glands. "Because IFI44 is overexpressed in head and neck squamous cell carcinoma cells and is significantly associated with clinical outcome, it is considered a potential prognostic indicator of this disease." (PMID 35047003, 2021). "Ifi44 is abnormally expressed in head and neck squamous cell carcinoma as compared to normal tissues." (PMID 34836197, 2021). "The results displayed that IFI44 was mainly located in the cytoplasm and overexpressed in head and neck squamous cell carcinoma (HNSC) samples compared with normal tissues." (PMID 33123469, 2020).
hepatitis C (3 papers, 2014 to 2021). "IFI44 gene is a member of the IFNs (IFNα/β) inducible gene family and may function as a mediator of antiviral activity against hepatitis C or D virus infections through interferons." (PMID 25012085, 2014). "IFI44, previously known as MTAP44, was first identified in the context of hepatitis C virus infection." (PMID 32611756, 2020).
interstitial lung disease (3 papers, 2016 to 2024). A diverse group of lung diseases that affect the lung parenchyma. "IFI44 has been reported to be upregulated in the lungs of an infant patient suffering from interstitial lung disease." (PMID 39609844, 2024). "The expression levels of interferon-regulated genes (OAS1 and IFI44) were found to be positively correlated with progressive lung fibrosis in patients with systemic sclerosis (SSc)–related interstitial lung disease (ILD)." (PMID 36061178, 2022). "A number of genes, such as Bst2, Rsad2, Ifi44, Oas2 and Stat2, were previously found to be downregulated in pulmonary fibroblasts from IPF patients and from scleroderma-associated interstitial lung disease." (PMID 27428020, 2016).
Sepsis (3 papers, 2021 to 2023). Sepsis is defined as life-threatening organ dysfunction caused by a dysregulated host response to infection. "The specific expression of IFI44 and IFIH1 in B cells with high PANscores underscores their pivotal role in modulating immune responses in sepsis." (PMID 38239341, 2023). "We observed an upregulation in the expression of IFI44, IFIH1, IFIT1, IFIT2, and RSAD2 in lung tissues from animals suffering from sepsis." (PMID 38239341, 2023). "IFI44 and IFIH1 were specifically expressed in cell populations with a high PANScore, potentially linking these genes to active immune responses in B cells and implicating them in the pathophysiology of sepsis." (PMID 38239341, 2023). "Additionally, ZBP1, XAF1, IFI44L, SOCS1, and PARP14 were notably high in HighPANscore cells, aligning with our observations of upregulated expression of IFI44, IFIH1, IFIT1, IFIT2, and RSAD2 in lung tissues from sepsis-induced animal models." (PMID 38239341, 2023).
colitis (2 papers, 2017 to 2025). Inflammation of the colon. "Genes such as C3, Ccl2, Cxcl1, Ifi44, Lcn2, S100a8, and Tnf were strongly induced during colitis, mirroring previously reported inflammation-associated transcriptional responses." (PMID 40806068, 2025). "After induction of acute colitis with DSS, we found with EdgeR and CuffDiff2 analyses that the expression of 11 genes (Clps, Ddx60, Fgb, Fgg, Ifi44, Ifit2, Isg15, Itih3, Itih4, Oas3 and Usp18), which are involved in antimicrobial response, was increased in MMP-9−/− compared to WT mice." (PMID 28561062, 2017).
Hepatitis (2 papers, 2013 to 2024). Inflammation of the liver. "IFI44 (p44) was chosen since p44 was the first cytoplasmic protein formerly shown to be associated with a characteristic ultrastructural entity (membranous web) within hepatocytes in nonA-nonB hepatitis, and it was later on found to be IFN-inducible." (PMID 24376784, 2013). "ISGs that were more highly expressed in hepatocytes in the HBeAg‐positive infection phase than in the hepatitis phases, including IFI44, ISG15, IFI44L, MX1, and OAS3, were not correlated with ALT levels." (PMID 39135698, 2024).
HIV-1 infection (2 papers, 2019 to 2025). The type species of lentivirus and the etiologic agent of acquired immunodeficiency syndrome (AIDS). "Surprisingly, however, both at the eclipse phase of infection as well as during late-stage chronic infection, HIV-1 infection suppressed baseline levels of IFI44 and showed similar trends with SAMHD1 and MX2 expression, indicating that HIV-1 actively shapes its environment." (PMID 30867315, 2019).
mesothelioma (2 papers, 2022 to 2025). A usually malignant and aggressive neoplasm of the mesothelium which is often associated with exposure to asbestos.
systemic sclerosis (2 papers, 2021 to 2022). A chronic disorder, possibly autoimmune, marked by excessive production of collagen which results in hardening and thickening of body tissues. "Interferon induced protein 44 (IFI44) may be involved in vascular lesions and pathogenesis of systemic sclerosis (SSc), and is also associated with immune and inflammatory diseases." (PMID 34753383, 2021).
tuberculosis (2 papers, 2022 to 2023). A chronic, recurrent infection caused by the bacterium Mycobacterium tuberculosis. "In contrast, the precise role of IFI44 in tuberculosis has yet to be revealed." (PMID 36845395, 2023). "Many interferon pathway-related genes, including STAT1,GBP1,GBP5, IFI44, IFIH1, FITM3, have been described in whole-blood transcriptome studies of tuberculosis." (PMID 36059536, 2022).
uveitis (2 papers, 2025). An inflammatory process affecting a part of or the entire uvea. "Among these, IFI44, IFI44L, and IRF9, were identified as having a significant effect on diagnosing insomnia-associated uveitis." (PMID 39958336, 2025). "Additionally, further in-depth investigation of IFI44 and IRF9 involvement in insomnia and uveitis is warranted and IFI44 and IRF9 should be assessed as therapeutic targets." (PMID 39958336, 2025). "We hypothesize that the upregulation of IFI44 in patients with insomnia may promote the progression of uveitis by inducing innate immunity, activating acquired immunity, and modulating inflammatory cytokine and antibody levels." (PMID 39958336, 2025). "Several metaDEGs from the uveitis only group, including IFIT3, IFI44, IFITM1, MX1, TLR7 and DHRS9, and gene hubs from the modular co-expression analyses of the systemic disease-associated uveitis group are critical players in interferon-induced immune responses." (PMID 40270958, 2025).
adenoma (1 paper, 2024). A neoplasm arising from the epithelium. "Top over-represented EV proteins from the adenoma ZMTH3 were mainly related to immune response (ISG15, BST2, IFI44), while top under-represented proteins identified in the adenoma ZMTH3 EVs were associated with migratory and adhesion activity (MXRA8, TNN, SERPINB8), similar to the WCLs." (PMID 39462388, 2024).
anemia (1 paper, 2022). A reduction in the number of red blood cells, the amount of hemoglobin, and/or the volume of packed red blood cells. "Anemia was seen in nearly half of the SLE patients in this study, and the expression levels of RSAD2, USP18, and IFI44 were lower in those patients." (PMID 35967341, 2022).
astrocytoma (1 paper, 2013). "We confirmed the contribution of ZNF395 in the IFN-α-dependent stimulation of ISG56 and IFI44 expression in the astrocytoma cell line U87-MG." (PMID 24086395, 2013).
Babesia infection (1 paper, 2021). "Although the mechanism of IFI44 involvement in defending against B. microti infection currently remains unclear, IFI44 might be able to be used as a marker for screening Babesia infection." (PMID 33468223, 2021).
bladder cancer (1 paper, 2017). "In bladder cancer cells, DAC treatment increased the double-stranded RNA sensors, MDA5, MAVS and RIG-1, intermediate mediator IRF7, and downstream targets IFI44 and IFI27 and IFN-γ by 2-fold to 70-fold compared to control cells." (PMID 29242529, 2017).
bronchiolitis (1 paper, 2023). Inflammation of the bronchioles characterized by swelling of the bronchioles and mucus accumulation. "IFI27, together with other genes that were differentially expressed, such as IFI44, OAS3, EPSTII, and IFI44L, are generally significantly up-regulated in whole blood from infants admitted to hospital with severe RSV-bronchiolitis." (PMID 36622786, 2023).
cervical squamous cell carcinoma (1 paper, 2020). A squamous cell carcinoma arising from the cervical epithelium. "In the case of cervical squamous cell carcinoma, the expression of IFI44 was observed to be higher in tumor parenchyma compared with the stroma region." (PMID 33123469, 2020). "Together, the immunohistochemistry results demonstrated the same upregulation of IFI44 in head and neck and cervical squamous cell carcinoma." (PMID 33123469, 2020).
Co-infection (1 paper, 2025). "In the current study, in the Tb+ group, IFI44 was markedly upregulated in the CF (1003-fold) and gills (362-fold) 1 day post-co-infection, likely due to a primary immune priming by T. bryosalmonae infection." (PMID 40943072, 2025). "In the caudal fin, Mc+ (1 day after co-infection with T. bryosalomne) fish showed mild immune activation with C4B upregulation, while Tb+ fish exhibited a stronger response involving IFI44, ISG15, RSAD2, and TLR7 signaling." (PMID 40943072, 2025).
colon cancer (1 paper, 2024). "We selected eight representative immune-related molecules for qPCR validation in SW480 and another colon cancer cell line HT29: DDX58, CHST4, TNFSF18, XAF1, OAS1, IFI27, IFI44, IFIT3." (PMID 38281029, 2024). "DDX58, XAF1, OAS1, IFI27, IFI44 or IFIT3 was indeed downregulated and CHST4 or TNFSF18 was upregulated in MDM4 overexpressed colon cancer cells." (PMID 38281029, 2024).
diabetic foot ulcer (1 paper, 2025). "This study employed machine learning techniques to identify four key genes—DPYSL2, CIB2, IFI44, and SAMHD1—that potentially play a significant role in the pathogenesis and progression of diabetic foot ulcer (DFU) disease." (PMID 40487403, 2025).
glioma (1 paper, 2021). A benign or malignant brain and spinal cord tumor that arises from glial cells (astrocytes, oligodendrocytes, ependymal cells). "In addition, we verified the association of SPON2 and IFI44 genes with macrophage recruitment and performed immunohistochemical staining on glioma samples for SPON2, IFI44, the macrophage marker CD68, and the M2 macrophage marker CD206." (PMID 34136486, 2021). "Our study showed that IFI44 was positively correlated with macrophage infiltration in gliomas." (PMID 34136486, 2021). "The immunostaining score evaluated by two professional pathologists showed that SPON2, IFI44, CD68, and CD206 were significantly overexpressed in high-grade gliomas." (PMID 34136486, 2021).
hepatitis D (1 paper, 2020). "The IFI44 is one of the interferon-α-stimulated genes that is associated with hepatitis D and limited scleroderma." (PMID 33101364, 2020).
Hypoglycemia (1 paper, 2023). A decreased concentration of glucose in the blood. "Thus, hypoglycemia in GHR-KO pigs might contribute to the reduced IFI44 protein abundance in CD4− PBMCs." (PMID 37189345, 2023).
inflammatory bowel disease (1 paper, 2025). A spectrum of small and large bowel inflammatory diseases of unknown etiology. "Inflammatory bowel disease was inversely associated with GATE scores for 5 interferon-stimulated genes—IFIT1, IFI44, HERC5, MX1, IFI44L—regulated by the same trans-expression quantitative trait locus, and with the GATE score for IFNL1." (PMID 40996888, 2025).
inflammatory skin disease (1 paper, 2021). Inflammatory skin disorders covers a broad category that includes many conditions ranging in severity, from mild itching to grave medical health complications These disorders are common in people of all ages and races. "Likewise, under AZ(−) conditions, THDC increased expression of genes belonging to the STAT1-57 module (P < 0.01), which is a set of genes activated by interferon signaling with elevated expression in inflammatory skin disease (e.g., MX2, IFIT3, IFI44)." (PMID 34445461, 2021).
insomnia (1 paper, 2025). A sleep disorder characterized by difficulty in falling asleep and/or remaining asleep. "Our study demonstrated involvement of the viral response in both insomnia and AU and identified the diagnostic significance of IFI44 and IRF9 in these conditions." (PMID 39958336, 2025). "Our study identified the diagnostic significance of IFI44 and IRF9 in insomnia-associated AU; however, this study has some limitations." (PMID 39958336, 2025).
Kidney Clear Cell Carcinoma (1 paper, 2026). "Using integrative transcriptomic analysis of the Gene Expression Omnibus and the Cancer Genome Atlas-Kidney Clear Cell Carcinoma cohorts, we first identified IFI44 as a key candidate gene." (PMID 41799288, 2026).
kidney damage (1 paper, 2025). "The expression level of IFI44 in the kidneys of LN patients was significantly up-regulated and closely correlated with the extent of kidney damage compared to normal individuals." (PMID 40101924, 2025).
latent infection (1 paper, 2014). "Moreover, we profiled the IRF4 transcriptome in the context of EBV latent infection, and confirmed several genes including IFI27, IFI44, GBP1, and ARHGAP18, as well as CFLAR as novel targets for IRF4." (PMID 25207815, 2014).
leukemia (1 paper, 2024). A malignant (clonal) hematologic disorder, involving hematopoietic stem cells and characterized by the presence of primitive or atypical myeloid or lymphoid cells in the bone marrow and the blood. "Combined multi-omics data pinpointed three upregulated genes (SDC2, NCAM2, and IFI44) that showed negative effects on survival in a larger leukemia cohort." (PMID 39399221, 2024).
liver fibrosis (1 paper, 2025). "Our study showed a significant increase in Ifi44 expression in the CCl4-induced liver fibrosis model, dependent on Type I IFN signaling." (PMID 40260261, 2025). "In this study, IFNα, IFNβ, ISG15, USP18, IFN-induced protein 44 (Ifi44), interferon-induced protein with tetratricopeptide repeat (Ifit) 1, Ifit2, IRF3, and IRF7 were significantly elevated in the CCl4-induced liver fibrosis model." (PMID 40260261, 2025).
lung disease (1 paper, 2021). "By specific lung cell isolation, several interferon-related and autoimmune genes were disproportionately expressed among CIA and CIA+ODE (e.g. Oasl1, Oas2, Ifit3, Gbp2, Ifi44, and Zbp1), corresponding to RA and RA-associated lung disease." (PMID 33577605, 2021).
lymphoma (1 paper, 2014). A malignant (clonal) proliferation of B- lymphocytes or T- lymphocytes which involves the lymph nodes, bone marrow and/or extranodal sites. "In addition, we have identified a panel of novel transcriptional targets including IFI27, IFI44, GBP1, CFLAR and ARHGAP18 for IRF4 in lymphomas." (PMID 25207815, 2014).
nasopharyngeal carcinoma (1 paper, 2020). A carcinoma arising from the nasopharyngeal epithelium. "The KEGG pathway analysis in Cytoscape also exhibited that IFI44 was associated with the process of EBV infection, which was referred to the progression of nasopharyngeal carcinoma (NPC)." (PMID 33123469, 2020).
oral carcinoma (1 paper, 2020). "In particular, increased expression of IFI44 was found in laryngeal, nasopharyngeal, tongue, and oral carcinoma." (PMID 33123469, 2020).
oral cavity carcinoma (1 paper, 2020). A carcinoma arising in the oral cavity. "Relatively, the prognosis of oral cavity carcinoma (OCC) was closely related to IFI44 mRNA expression level." (PMID 33123469, 2020).
oropharyngeal squamous cell carcinoma (1 paper, 2020). "Consistently, analysis of human papillomavirus (HPV) positive oropharyngeal squamous cell carcinoma showed the same distribution of IFI44 expression (GSE112026, 25 normal vs. 47 cancer, P < 0.0001)." (PMID 33123469, 2020).
osteosarcoma (1 paper, 2020). A usually aggressive malignant bone-forming mesenchymal neoplasm, predominantly affecting adolescents and young adults. "Three of highly expressed genes (DDX10, FOXA2, and HEY1) were correlated with poor prognosis, while three of lowly expressed genes (CYP26B1, GP1BB, and IFI44) showed the opposite trend in patients with osteosarcoma." (PMID 32284759, 2020). "High expression of CYP26B1, GP1BB, and IFI44 in osteosarcoma patients was correlated with good prognosis, while high expression of DDX10 and FOXA2 in osteosarcoma patients was associated with poor prognosis." (PMID 32284759, 2020).
pericardial effusion (1 paper, 2022). Fluid collection within the pericardial sac, usually due to inflammation. "The expression levels of USP18 and IFI44 were likewise lower in the serositis positive group, which included SLE patients with pleural effusion or pericardial effusion, than in SLE patients without serositis." (PMID 35967341, 2022).
polymyositis (1 paper, 2023). A rare idiopathic inflammatory myopathy characterized by symmetric proximal muscle weakness and elevated muscle enzymes. "Another study reported that the breakdown of positive IFN-I signatures (top five IFIGs were IFI6, RSAD2, STAT2, IFI44, and IFI27) in whole blood of patients were 73% SLE, 68% SSc, 66% DM, 61% polymyositis (PM), and 33% RA." (PMID 36979843, 2023). "Using microarrays, IFIG expression levels (including ISG5, Mx1, OAS1, IFIT4, IFIT1, IFI44, OAS3, OAS2, IRF7, and IFI27) in muscle samples were higher in DM than in other inflammatory myopathies, such as inclusion body myositis, polymyositis, necrotizing myopathy, and myopathies with inflammation." (PMID 36979843, 2023).
pulmonary hypertension (1 paper, 2024). Increased pressure within the pulmonary circulation due to lung or heart disorder. "Finally, we show silencing IFI44 in the lungs of 15-HETE diet mice prevents the development of pulmonary hypertension." (PMID 39609844, 2024).
sarcoidosis (1 paper, 2022). Sarcoidosis is a multisystemic disorder of unknown cause characterized by the formation of immune granulomas in involved organs. "In addition, we found that LRRN3, IFI44, LHFPL2, RTP4, and EPHX2 were all involved in diagnosing sarcoidosis, which might shed light on the mechanisms of sarcoidosis and provide potential biomarkers for diagnosis." (PMID 36405616, 2022).
SARS-CoV infection (1 paper, 2012). "Moreover, four IRGs (ISG15, IFI44, PSME2 and CCL2) were expressed in common between the SARS-CoV infection-reinfection experiments and these 8 IRGs." (PMID 23029269, 2012). "Interestingly, the temporal expression patterns of 4 IRGs (ISG15, IFI44, PSME2 and CCL2) were similar amongst the SARS-CoV infection-reinfection experiments (50 IRGs) and this list of 8 IRGs from the adjuvanted vaccine–challenge experiments." (PMID 23029269, 2012).
thrombosis (1 paper, 2024). "However, the presence and extent of recurrence of thrombosis were positively associated with the expression of IFI44, OAS1, and RSAD2 as well as with the IFN score in patients with SAPS." (PMID 38550580, 2024).
uterine disease (1 paper, 2022). "Pregnancy regulated genes downstream of AIRE in cows following uterine infection are all upregulated (EIF2AK2, IFI44, HERC6, PARP14, TNFSF10), suggesting the dysregulated expression of these genes could be important for pregnancy establishment following uterine disease." (PMID 35358206, 2022).
ZIKV infection (1 paper, 2025). "The results showed that all genes were significantly upregulated in the infected group, with IFI44 and IFI27 showing the most significant upregulation, indicating that these genes may be involved in the regulation of the host’s response to ZIKV infection in the nervous and immune systems." (PMID 41573570, 2025).